CMC4 (C-X9-C motif containing 4)
Synonyms: p8MTCP1; C6.1B; MTCP1; MTCP1NB; p8; MTCP1B
Tractability: PROTAC: ubiquitination databases record sites on it; its protein half-life has been measured.
Gene: Protein-coding gene on chromosome X (155,061,622 to 155,071,136, reverse strand). Ensembl gene ENSG00000182712.
Subcellular location: Mitochondrion
Subcellular location (Human Protein Atlas): Mitochondria
Pathways (Reactome):
Protein localization: Mitochondrial protein import
Gene Ontology:
Cellular component: mitochondrion; mitochondrial intermembrane space
Homologues: Orthologues: chimpanzee CMC4 (97% identical), rabbit CMC4 (91% identical), dog CMC4 (88% identical), mouse Cmc4 (88% identical), guinea pig CMC4 (85% identical), pig CMC4 (85% identical), Drosophila melanogaster CG42381 (38% identical).
Diseases named in the same sentence as CMC4 in open-access papers:
CMC4 is named in the same sentence as 13 diseases in open-access papers, as found by Europe PMC text mining. Sharing a sentence is not in itself a finding about the gene and the disease. The quoted sentences say what the papers report.
hemophilia A (2 papers, 2015 to 2020). The most common form of hemophilia characterized by spontaneous or prolonged hemorrhages due to factor VIII deficiency. "Recently, an ~150 kb deletion of Xq28 encompassing part of F8, FUNDC2, CMC4, MTCP1, and BRCC3 was reported in a child with severe hemophilia A, Moyamoya disease, and distinctive facial features." (PMID 25927380, 2015). "This is consistent with the absence of hemophilia A or moyamoya disease in the patient and also suggests a link between loss of function of FUNDC2 and CMC4 and the patient’s phenotype." (PMID 33193636, 2020).
Moyamoya disease (2 papers, 2015 to 2020). Moyamoya disease (MMD) is a rare intracranial arteriopathy involving progressive stenosis of the cerebral vasculature located at the base of the brain causing transient ischemic attacks or strokes. "The critical region of overlap for syndromic moyamoya disease among these three families encompasses exon 1 of CMC4 and MTCP1 and the first three exons of BRCC3." (PMID 33193636, 2020). "Deletions including FUNDC2, CMC4, MTCP1, and BRCC3 were reported in individuals with syndromic Moyamoya disease, characterized by angiopathy, short stature, and distinctive facial features." (PMID 25927380, 2015). "Further experiments in this study using Zebrafish models demonstrated that deletion of BRCC3 but not CMC4 results in defective angiogenesis, further confirming the role of BRCC3 in moyamoya disease." (PMID 33193636, 2020).
chronic lymphocytic leukemia (1 paper, 2023). "In addition, the over-expression of CMC4 (also known as MTCP1), as a favorable prognosis gene in our model, was discordantly reported to produce clonal CD5+/CD19+ leukemia in mice, which was thought to be a chronic lymphocytic leukemia driving gene." (PMID 36816541, 2023).
genetic disorders (1 paper, 2020). "Our study provides novel insights into how loss of CMC4 and FUNDC2 contributes to dysregulation of apoptosis, inflammatory response, and HH and demonstrates the effectiveness of RNA-seq as a way to characterize gene function as part of understanding gene dosage in genetic disorders." (PMID 33193636, 2020).
tumor (1 paper, 2020). "One recent study using the nude mouse tumor model showed that suppression of CMC4 (misnamed as MTCP1 in this study, since the antibody used is for the peptide encoded by CMC4) by miR-126 is involved in repression of tumor growth and migration." (PMID 33193636, 2020).
CMC4 also shares sentences with these, for which no sentence is quoted: infection (2 papers); cataract (1); Duodenal stenosis (1); Gynecomastia (1); hemophilia (1); Hypergonadotropic hypogonadism (1); Klinefelter syndrome (1); leukemia (1).